DGCR6 (DiGeorge syndrome critical region gene 6)
Description:
May play a role in neural crest cell migration into the third and fourth pharyngeal pouches.
Tractability: Antibody: its Gene Ontology location is reachable by antibodies, with high confidence. PROTAC: ubiquitination databases record sites on it.
Gene: Protein-coding gene on chromosome 22 (18,905,677 to 18,914,281, forward strand). Ensembl gene ENSG00000183628.
Subcellular location: Nucleus
Gene Ontology:
Molecular function: protein binding
Biological process: animal organ morphogenesis; cell adhesion
Cellular component: extracellular matrix; nucleus
Homologues: Orthologues: chimpanzee DGCR6 (99% identical), macaque DGCR6 (97% identical), macaque DGCR6L (97% identical), dog DGCR6L (86% identical), guinea pig Dgcr6l (84% identical), mouse Dgcr6 (83% identical), rat Dgcr6 (83% identical), tropical clawed frog dgcr6 (63% identical), zebrafish dgcr6 (58% identical), Drosophila melanogaster gdl (32% identical). Paralogues in human: DGCR6L (97% identical).
Diseases named in the same sentence as DGCR6 in open-access papers:
DGCR6 is named in the same sentence as 11 diseases in open-access papers, as found by Europe PMC text mining. Sharing a sentence is not in itself a finding about the gene and the disease. The quoted sentences say what the papers report.
schizophrenia (8 papers, 2016 to 2025). A major psychotic disorder characterized by abnormalities in the perception or expression of reality. "The researchers provide evidence for a contribution of the Profline dehydrogenase 2 (PRODH2)/DiGeorge syndrome critical region gene 6 (DGCR6) locus in 22q11-associated schizophrenia, in three independent samples." (PMID 35547101, 2022). "This region spanned the DiGeorge syndrome critical region gene 5 and 6 (DGCR5 and DGCR6) as well as the proline dehydrogenase 1 (PRODH) gene implicated in schizophrenia and hyperprolinemia type 1." (PMID 26933844, 2016). "DGCR6 variants have been associated with schizophrenia susceptibility and brain connectivity, suggesting that duplications of this gene might have downstream effects on behavioral regulation." (PMID 41510264, 2025). "For schizophrenia, DGCR6 and PRODH are well-known candidate genes, and DGCR5 is a long non-coding RNA gene with a high score for causing schizophrenia." (PMID 37486921, 2023). "Among the top 40 genes associated with developmental delay, DGCR6, PRODH, DGCR5, and ZDHHC8 are potential candidates for involvement in DiGeorge syndrome pathology and schizophrenia." (PMID 37486921, 2023). "Refseq genes in this region include FAM230F, DGCR6, PRODH, DGCR5, with pathogenic PRODH variants associated with autosomal recessive hyperprolinemia type I or autosomal susceptibility to schizophrenia." (PMID 34938854, 2021). "One of the well-known candidate genes for schizophrenia is DGCR6, which codes for a protein." (PMID 37486921, 2023). "Heterozygous pathogenic variants in PRODH have been associated with an increased risk of schizophrenia, and proximal deletions excluding TBX1 but showing syndromic features (particularly neurological ones) have suggested candidate genes such as DGCR6 (OMIM *601279) and PRODH." (PMID 41165438, 2025).
DiGeorge syndrome (6 papers, 2016 to 2025). "DGCR6 is associated with DiGeorge syndrome, a consequence of microdeletions in chromosomal region 22q11.2 and also has increased levels in metastatic mammary tumour cells." (PMID 28382934, 2017). "Our cell-type-specific findings may offer new insights into the regulatory roles of DGCR6, particularly in how its expression in MonoC might influence platelet dynamics, potentially informing the mechanisms underlying 22q11.2 deletion syndrome." (PMID 41256005, 2025). "Furthermore, DGCR6, located in the 22q11.2 region, is a candidate for involvement in DiGeorge syndrome (22q11.2 deletion syndrome) pathogenesis." (PMID 41256005, 2025). "DGCR6, duplicated in five patients affected by CL, CLP and CP, has been proposed in literature to be involved in the developmental defects associated with 22q11.2 deletions syndrome (aka DiGeorge syndrome) (OMIM*601279)." (PMID 26561393, 2016). "In 2012, researchers reported on dysregulation of DGCR6 and DGCR6L and the psychopathological outcomes in chromosome 22q11.2 deletion syndrome." (PMID 35547101, 2022).
anxiety disorder (2 papers, 2020 to 2022). A category of psychiatric disorders which are characterized by anxious feelings or fear often accompanied by physical symptoms associated with anxiety. "Their investigation revealed that low expression levels of the vital genes DGCR6 and DGCR6L are associated with the observed variability in anxiety disorders in children with 22q11 deletion syndrome." (PMID 35547101, 2022). "Significantly lower DGCR6 expression was found in children with 22q11 DS who had anxiety disorders." (PMID 33510659, 2020).
hyperprolinemia type 1 (2 papers, 2016 to 2021). Hyperprolinaemia type I is an inborn error of proline metabolism characterized by elevated levels of proline in the plasma and urine. "A recent case control study reported microdeletions encompassing the PRODH and DGCR6 genes to be a strong risk factor for hyperprolinemia type 1 but not for autism spectrum disorder suggesting more emphasis on the other lesser known FAM230F and DGCR5 genes." (PMID 34938854, 2021).
psychiatric disorder (1 paper, 2025). A disorder characterized by behavioral and/or psychological abnormalities, often accompanied by physical symptoms. "The 22q11.21 rCNV associated with “Any psychiatric disorder” in this study duplicates genes plausibly altering brain function: USP18, DGCR6, and PRODH." (PMID 41510264, 2025).
DGCR6 also shares sentences with these, for which no sentence is quoted: autism (1 paper); autism spectrum disorder (1); developmental delay (1); diseases of the larynx and vocal cords (1); mammary tumour (1); thoracic aortic aneurysm (1).